NF2 (NF2, moesin-ezrin-radixin like (MERLIN) tumor suppressor)
Diseases named in the same sentence as NF2 in open-access papers (continued):
Sharing a sentence is not in itself a finding about the gene and the disease.
meningioma (continued). "In meningioma, an inactivating mutation of a tumor suppressor gene, the neurofibromatosis type 2 (NF2) gene, is a well-known genetic alteration." (PMID 32742192, 2020). "TRAF7 mutations are present in approximately 25% of sporadic meningiomas, and studies have revealed they are mutually exclusive from NF2 mutant tumors, yet larger studies are need to confirm exclusivity of TRAF7 mutant tumors." (PMID 33346248, 2020). "Merlin-deficient meningioma arise when both alleles of the Neurofibromin 2 gene (NF2) are mutated, which underlie the genetic condition neurofibromatosis type 2 (NF2), and occur sporadically in more than 50% of meningioma." (PMID 32629964, 2020). "Results of this study contribute to a better understanding of NF2-associated meningiomas clinical behavior and their genetic underpinnings." (PMID 32724039, 2020). "SMARCB1 is very closely associated to NF2 on chromosome 22, and co-mutation of both genes has been seen with tumorigenesis of meningiomas." (PMID 33194703, 2020). "We performed a drug screening using human malignant meningioma cell lines IOMM-Lee (NF2 wildtype), CH157-MN (NF2-deficient), and a 20 agent-library encompassing both targeted agents and cytotoxic chemotherapeutics." (PMID 32642722, 2020). "As mentioned briefly above, the most common cytogenetic aberration observed in meningiomas is deletion or loss of genetic loci containing the neurofibromin 2 (NF2) gene on chromosome 22q." (PMID 33330036, 2020). "Compared with other anatomic locations, NF2 mutations are more common in the lateral regions and posterior skull base meningiomas, while the most majority of non-NF2 meningiomas often locate in the anterior, medial, or skull base regions." (PMID 33042832, 2020). "When low- and high-grade tumors from a single patient were analyzed, NF2 loss was exhibited in both low and high grade tumors suggesting that NF2 loss is an early event in meningioma progression." (PMID 33346248, 2020). "In summary, we have demonstrated for the first time that NF2-associated meningiomas are especially sensitive to ICG-001 in vitro and in vivo partly because of the attenuation of the FOXM1-mediated Wnt/β-catenin signaling." (PMID 32642722, 2020). "FBXW7 mutations were present in 23/472 of all NF2-mutant (4.9%) and in 3/377 of NF2-wt meningiomas (0.8%) (p = 0.0004)." (PMID 33087175, 2020). "Meningiomas express Hedgehog genes, and the majority of Hedgehog pathway variants in meningiomas are mutually exclusive from NF2 variants." (PMID 32690089, 2020). "In the present study, all the sample groups had mutations in the meningioma-driver genes such as NF2, AKT1, SMO, TRAF7, and KLF4." (PMID 32742192, 2020). "Additional large-scale drug screening studies are underway for NF2-associated meningioma and schwannoma to identify additional therapeutic targets." (PMID 31161239, 2020). "NF2-associated VSs are often accompanied by meningioma (MN), and the majority of NF2 patients show loss of the NF2 tumor suppressor." (PMID 32144278, 2020). "NF2-associated meningiomas occur most frequently in the supratentorial region in the frontal, parietal, and temporal regions as well as along the falx cerebri." (PMID 31161239, 2020). "Meningiomas that occur due to NF2 mutations tend to be transitional or fibroblastic, and are located in the convexity or (lateral or posterior) skull base, whereas non-NF2 meningiomas are more medially located." (PMID 32070062, 2020). "We have established that the endpoint genotyping method Kompetitive Allele Specific PCR (KASPTM) is a fast, reliable method for the screening of meningioma samples into different non-NF2 mutational groups using a standard real-time PCR instrument." (PMID 32070062, 2020). "The frequency of NF2 mutations increased significantly with the WHO grade: 81/220 of grade 1 (36.8%), 265/441 of grade 2 (60.1%, p = 0.0001) and 122/176 of grade 3 (69.3%, p = 0.0001) meningiomas harbored NF2 mutations." (PMID 33087175, 2020).
meningioma (continued). "NF2 status was then assessed by either intact Merlin protein (non-NF2 meningiomas) or Merlin loss (NF2 meningiomas)." (PMID 32070062, 2020). "TERTp mutations occurred in 35/441 (8.1%) of NF2-mutant meningiomas and in 21/348 of NF2-wt patients (5.7%, p = 0.21)." (PMID 33087175, 2020). "NF2-associated meningiomas appear to arise less frequently at locations in the anterior and middle skull base, similar to sporadic NF2-mutated meningiomas which have a predilection for the dura overlying the cerebral convexities." (PMID 31161239, 2020). "Surgery is also frequently applied in NF2 associated ependymomas and meningiomas if they become symptomatic." (PMID 32244314, 2020). "PIK3CA, located on chromosome 3q26.3 encodes the p110 alpha catalytic subunit of PI3K, occurs in 7% of non-NF2 associated grade I meningiomas, and has been reported in grade 2 and grade 3 tumors." (PMID 33346248, 2020). "Fifty to sixty percentage of meningiomas patients have mutation of tumor suppressor gene neurofibromatosis type 2 (NF2)." (PMID 32974188, 2020). "DNA alterations, in special DNA methylation, are highly associated with meningioma progression, especially as a discriminant feature between NF2-mutated and non-NF2-mutated tumours." (PMID 31865413, 2020). "The SB location corresponded to the anterior and middle cranial fossae in one and three cases, respectively, in contrast to the predominant posterior fossa location reported for NF2-mutated meningiomas, in general." (PMID 31963394, 2020). "Some WHO grade I meningiomas are linked to mutations of the NF2 gene on chromosome 22 (location q12.2), which leads to the condition known as neurofibromatosis type II where benign tumour proliferates through the CNS." (PMID 31865413, 2020). "Alterations in chromosome 10, including the PTEN gene located near the p23.3 region of chromosome 10, and other genetic non-NF2 aberrations are associated with higher-grade meningiomas." (PMID 31865413, 2020). "Recently several non-NF2 mutations in meningioma have been identified and correlated with certain pathological subtypes, locations and clinical observations." (PMID 32245394, 2020). "In fact, recent genetic studies demonstrated that tentorial meningiomas had a relatively high NF2 mutation rate, similarly as observed for NSB tumors." (PMID 33305267, 2020). "In conclusion, NF2-associated benign symptomatic cranial meningiomas had significantly larger volumes than meningiomas in the spine; however, the relative growth rates of cranial and spinal tumors were similar and low." (PMID 32724039, 2020). "Allelic losses (loss of heterozygosity (LOH)) of this region are found in 40–70% of sporadic and the vast majority of NF2 associated meningiomas." (PMID 32670372, 2020). "In an examination of NF2 mutated meningiomas, upregulated proteins combined either a PDZ/LIM domain which play a wide role in biological functions, specifically cell signaling." (PMID 33346248, 2020). "The specific mutations involved in meningioma oncogenesis can be broadly categorized as tumors harboring NF2 mutations and tumors harboring mutations other than NF2." (PMID 33346248, 2020). "A case series examining 287 cranial meningiomas from NF2 patients confirmed that similar to their sporadic counterparts, the majority of NF2-associated meningiomas (95.8%) were grade 1 by WHO guidelines." (PMID 32724039, 2020). "Approximately half of all sporadic meningiomas harbor an NF2 mutation with the remaining 50% of meningiomas harboring an alteration in one or a combination of several other genes involved in meningioma oncogenesis." (PMID 33346248, 2020). "While each gene variant has provided further information on the biology of meningioma; monosomy, NF2 and TRAF7 seem to be the driving forces in tumorigenesis." (PMID 33346248, 2020).
meningioma (continued). "Each subtype of meningiomas has its own molecular features, but some genetic mutations (including NF2, TRAF7, AKT1, and PIK3CA) can be found among several subtypes of meningiomas, which confuse the judgment of tumor evolution." (PMID 33014773, 2020). "The most common mutations found in meningioma involve the NF2 gene, with up to 60% of tumors demonstrating somatic inactivation of NF2." (PMID 31963394, 2020). "Dysregulation of RAS–MEK–ERK and mTORC1/2 signaling has been shown to promote tumorigenesis in NF2-associated schwannomas and meningiomas, and inhibition of these pathways has shown promise in multiple therapeutic trials in NF2 patients." (PMID 31161239, 2020). "Our results showed that the primary atypical meningioma has an NF2 deletion mutation in the tumor sample as well as in the primary cancer cell lines." (PMID 32742192, 2020). "Multi-focal presentation is more common in NF2-associated lesions (35% vs. 13% of sporadic lesions), as with other NF2-associated lesions such as schwannomas and meningiomas." (PMID 31161239, 2020). "In 60–80% of sporadic meningiomas, the mutation in neurofibromatosis type 2 gene (NF2) leading to its inactivation occurs." (PMID 32493231, 2020). "PTEN mutations were identified in 28/472 of all NF2-mutant (5.9%) and in 10/376 of NF2-wt meningiomas (2.6%) (p = 0.0287)." (PMID 33087175, 2020). "Loss of NF2 function or loss of heterozygosity at chromosome 22q, where NF2 is located, has been linked to sporadic higher grade meningiomas and poor prognosis." (PMID 32070062, 2020). "The occurrence of multiple meningiomas is a hallmark of NF2 and a major diagnostic criterion for the syndrome, occurring in about 50% of patients with NF2." (PMID 31161239, 2020). "Type B (a mixture of grade I and II tumors) meningiomas were characterized by chr22q/NF2 loss and co-occurrence of SMARCB1 mutations." (PMID 31652973, 2019). "Mutations in NF2 have been associated with the development of benign intracranial tumors, including schwannomas and meningiomas." (PMID 31191822, 2019). "Among the fusion transcripts identified, several involved the NF2 gene, the most common gene associated with meningioma tumorigenesis." (PMID 31039818, 2019). "NF2 is mutated in neurofibromatosis type II, a familiar tumor predisposition syndrome where up to 70% of patients develop meningiomas." (PMID 31039818, 2019). "In the present study, 8% of meningiomas with NF2 mutations were subtotally resected compared with 19% of non-NF2-driven meningiomas." (PMID 31191822, 2019). "Taken together with previous work, these results suggest that chr22q/NF2 loss is a requisite for the development of aggressive meningiomas which also harbor chr1p losses." (PMID 31652973, 2019). "Further, exposure to radiation therapy, a known risk factor for meningioma development, has been shown to drive structural aberrations in NF2." (PMID 31039818, 2019). "In NF2, various types of tumors including schwannomas, meningiomas, and ependymomas develop due to loss of the NF2 gene, which encodes for Merlin, a tumor suppressor protein." (PMID 31245296, 2019). "It is intriguing, however, that the two types of NF2-inactivated meningiomas (type B and C) seem to have different underlying molecular mechanisms and dramatically different clinical outcomes." (PMID 31652973, 2019). "NF2 mutations were found in 44% of the cases, while common genetic alterations in meningiomas of other locations (TRAF7, AKT1, SMO, KLF4, PIK3CA, and TERT) were lacking in non-NF2-associated cases." (PMID 31470906, 2019). "The tumor suppressor TRAF7, which exclusively occurs in non-NF2 meningiomas, is the second most altered gene with mutations occurring in approximately 25% of cases." (PMID 31470906, 2019). "Next-generation sequencing studies and increasingly sophisticated NF2-deletion-based in vitro and in vivo models have helped elucidate the consequences of merlin loss in meningioma pathogenesis." (PMID 31652973, 2019).
meningioma (continued). "The hallmark of NF2 is the development of bilateral vestibular schwannomas, although NF2 patients can develop other schwannomas, meningiomas, ependymomas, and astrocytomas." (PMID 31312020, 2019). "Within a large panel of clinically actionable driver mutations, matched primary and recurrent meningiomas exhibited similar genomic alterations, most commonly in NF2 and POLE genes." (PMID 31191822, 2019). "Less frequent, sporadic mutations occur in WHO°I and WHO°II meningiomas concurrently with NF2 mutations and are associated with poorer prognosis." (PMID 31470906, 2019). "More recently, TERT promoter mutations have been reported in ~6% of all meningiomas, with ~80% of these also harboring alterations (mutations or deletions) at the NF2 locus." (PMID 31970090, 2019). "NF2-mutated meningiomas show higher chromosomal instability during progression than non-NF2 mutated meningiomas." (PMID 31565188, 2019). "Among the meningiomas, the most common mutations were in NF2 (59/71), PIK3CA (22/71), FGFR3 (13/71), SMO (11/71) and AKT1 (10/71), with Tertp (1/71) mutations the least frequent." (PMID 31565188, 2019). "Enrichment in NF2 mutations has also been linked to features of high-grade meningiomas over low-grade." (PMID 31039818, 2019). "Sporadic meningiomas are mainly associated with focal chromosomal deletion and inactivation of neurofibromatosis type 2 (NF2) tumor suppressor gene on chromosome 22, which encodes a cytoskeletal-associated protein with an inhibitory effect on the cell cycle." (PMID 31477146, 2019). "When investigating the correlation between clinicopathological features and genotype, 80% of NF2-mutated meningiomas were found in the calvarium." (PMID 31565188, 2019). "NF2 alterations have been previously shown to be associated with schwannoma, ependymoma, and meningioma, and tuberous sclerosis with ependymoma." (PMID 31712784, 2019). "Subsequent studies in sporadic meningiomas demonstrated that up to 60% of these cases exhibit inactivation of NF2 by somatic mutation, epigenetic inactivation, or allelic loss of chr22q." (PMID 31652973, 2019). "Non-NF2 associated meningiomas are prone to a wide variety of mutations, many of which remain to be discovered." (PMID 31788444, 2019). "Third, while we provide a strong relationship between reduced PR and NF2 expression in serum and the increased risk of meningioma, the exact molecular mechanism of PR and NF2 in the tumorigenesis of meningioma remains less conclusive." (PMID 30687635, 2018). "NF2 manifests itself in the development of multiple schwannomas on cranial and peripheral nerves as well as of ependymomas and meningiomas that can only be treated surgically where loss-of function of the involved nerve is often an unpreventable consequence." (PMID 29626191, 2018). "In the non-NF2 meningiomas it was observed the frequent mutation of TRAF7, a proapoptotic ubiquitin ligase; a part of these meningiomas with mutated TRAF7 exhibited also KLF4 (a transcription factor involved in pluripotency) and AKT1 mutations." (PMID 30279357, 2018). "In this study, we aimed to examine the expression of PR and NF2 and assess their relationships to their history of exogenous progesterone use and risk of meningioma among females." (PMID 30687635, 2018). "NF2 is considered an initial driver of meningioma as it is mutated in both low- and high-grade meningioma, and mice with NF2-knockout develop spontaneous meningioma." (PMID 30082628, 2018). "The high occurrence of NF2 loss is associated in these atypical meningiomas with either genomic instability or SMARC1B mutations." (PMID 30279357, 2018). "NF2 is caused by a mutation in a tumour suppressor gene onchromosome 22q12 and is characterized by vestibular schwannomas and meningiomas." (PMID 31489219, 2018). "Among all mutations, the only known driver mutation causative of meningiomas was a frameshift deletion of NF2, which was present in both brain and lung tumors." (PMID 29764516, 2018).
meningioma (continued). "Initial studies aiming to characterize the genetic abnormalities occurring in meningiomas have shown the frequent loss of Neurofibromin 2 (NF2) gene, observed in 40–60% of these tumors (sporadic meningiomas)." (PMID 30279357, 2018). "More recently, a study comparing benign versus de novo atypical (grade II) meningiomas found the latter to be significantly associated with NF2 and SMARCB1 mutations." (PMID 30202034, 2018). "This study was aimed to examine expression of Progesterone receptor (PR) and Neurofibromatosis-2 (NF2) and assess their relationships to history of exogenous progesterone use and risk of meningioma." (PMID 30687635, 2018). "SMO mutations, which activate Hedgehog signaling, were identified in 5% of non-NF2 mutated meningiomas." (PMID 30279357, 2018). "Lower expression of PR and NF2 also showed a synergistic effect and associated with significant increase in the risk of developing orbitocranial meningioma." (PMID 30687635, 2018). "Our study also demonstrated novel findings that there was a significant interaction between PR and NF2 expression and increased risk of meningioma." (PMID 30687635, 2018). "PDGF activation in PGDS-positive arachnoid cells induces meningioma formation, whose extent was increased by combination of NF2 and CDKN2A loss." (PMID 30279357, 2018). "Although bilateral vestibular schwannomas are pathognomonic for NF2, meningiomas are the second most common tumor type in NF2 and their presence is associated with increased mortality." (PMID 29897904, 2018). "In NF2, tumors like schwannomas, meningiomas, and ependymomas develop due to the loss of the NF2 gene on chromosome 22." (PMID 29515781, 2018). "NF2 mutations are the most frequent in meningiomas, and loss of NF2 has been confirmed to cause meningioma in a mouse model." (PMID 29764516, 2018). "In meningioma, moesin labeled strongly the vessels and to a lesser extent the lumens and microlumens in the secretory variant and NF2 labeled the cytoplasm, more intensely in the secretory variant." (PMID 29983887, 2018). "The NF2 gene on chromosome 22 is mutated in Neurofibromatosis type II syndrome, and nearly 70% of these patients develop multiple meningiomas of different WHO grades, with grade I being the most common, along with other central nervous system tumors." (PMID 30082628, 2018). "In patients with neurofibromatosis type 2, who have germline NF2 mutations and are predisposed to forming schwannomas, meningiomas, gliomas or neurofibromas; truncating mutations have been associated with a poorer prognosis." (PMID 29731991, 2018). "Among these, loss of the NF-2 gene on chromosome 22q has been associated both with meningiomas arising in patients with neurofibromatosis syndrome and in up 60% of sporadic meningiomas." (PMID 30542514, 2018). "Neurofibromatosis Type 2 (NF2) is a genetic neoplastic disorder thatpresents with multiple meningiomas and bilateral vestibular schwannomas, and most meningiomas associated with NF2 arise intracranially." (PMID 31489219, 2018). "It is important to note that AKT1 and SMO mutations are selectively observed in a subset of non-NF2-mutated meningiomas (9% and 6% of cases, respectively); furthermore, PIK3CA mutations occurred in 7% of non-NF2-mutant meningiomas." (PMID 30279357, 2018). "NF2 alterations are the most frequent genetic abnormalities occurring in meningiomas and, thus, it is not surprising that various studies have explored the role of NF2 mutations in meningioma development in animal models." (PMID 30279357, 2018). "This is consistent with a study showing that individuals with certain mutations in the NF2 gene had increased risk of developing meningioma." (PMID 30687635, 2018). "Compared to the reference group, group with the lowest value of both NF2 and PR had the highest risk of meningioma (OR 21.0; 95% CI 4.01–109; P < 0.001)." (PMID 30687635, 2018).